BPI (bactericidal permeability increasing protein)
Diseases named in the same sentence as BPI in open-access papers (continued):
Sharing a sentence is not in itself a finding about the gene and the disease.
tumor (4 papers, 2018 to 2025). "Some anti‐angiogenic agents such as endostatin 21, vasostatin 22, thrombospondin 23, angiostatin 24, and BPI 25 have been successfully produced to inhibit the growth and adhesion of ECs, thus resulting in tumor cell apoptosis." (PMID 29659181, 2018). "In almost the same way, aberrant expression of TCAP and BPI was in relation with multiple types of tumor." (PMID 29760609, 2018). "Notably, higher levels of Sphingomonas in healthy mammary tissue compared to tumor tissue have been linked to increased expression of Toll-like receptors (TLR2, TLR5, and TLR9) and antimicrobial effectors such as IL-12A, bactericidal/permeability-increasing protein (BPI), and myeloperoxidase (MPO)." (PMID 40599853, 2025). "Innate immune system receptors such as TLRs 2, 5, 9, and the factors responsible for anti-microbial responses such as IL-12 subunit alpha (IL-12A), bactericidal/permeability-increasing protein (BPI), and myeloperoxidase (MPO) were expressed minor in the tumor in comparison with healthy tissue." (PMID 32117767, 2020).
cancer (3 papers, 2016 to 2025). A tumor composed of atypical neoplastic, often pleomorphic cells that invade other tissues. "Proteins, including TOP2A, BPI, PSAT1, ANLN, and TFRC, were upregulated in five of the six cancer types." (PMID 41049442, 2025).
BPI also shares sentences with these, for which no sentence is quoted: chronic obstructive pulmonary disease (4 papers); infectious disease (3); pneumonia (3); acute respiratory distress syndrome (1); allergic rhinitis (1); Allergy (1); bacterial pneumonia (1); bipolar disorder (1); coronary heart disease (1); Cryptococcal meningitis (1); diabetes mellitus (1); E. coli (1); endotoxemia (1); esophageal cancer (1); familial hypercholesterolemia (1); Hyperglycemia (1); Insulin resistance (1); liver disease (1); major depression (1); malaria (1); meningococcal meningitis (1); microscopic polyangiitis (1); myositis (1); nasal polyp (1); Neonatal sepsis (1); neutropenia (1); osteomyelitis (1); pancreatic cancer (1); Pseudomonas infection (1); psoriasis (1).
A further 10 diseases each share a sentence with BPI in 1 paper.